CRP (C-reactive protein)
Diseases named in the same sentence as CRP in open-access papers (continued):
Sharing a sentence is not in itself a finding about the gene and the disease.
COVID-19 (continued). "Increased C-reactive protein (CRP) levels, cytopenia, prolonged prothrombin time, elevated D-dimer values, and high troponin levels can be evaluated for and seen in severe cases of COVID-19 patients in particular." (PMID 36324350, 2022). "After exclusion of COVID-19 patients, PSP performed slightly better than CRP or WBC." (PMID 35631080, 2022). "CRP, IL-6, D-dimers, fibrinogen, and ferritin were significantly different after comparing survivors with non-survivors and non-severe with severe COVID-19 patients." (PMID 35207531, 2022). "More so, with neutrophil migration and cell death (IL-1α) contributing much to COVID-19 pathology (Gupta 2020a, b), suPAR can be a better early biomarker than non-specific markers (PCT/CRP) for COVID-19 progression." (PMID 35431536, 2022). "DVT in the recent COVID-19 group was associated with significantly higher neutrophils, D-dimers, LDH and CRP, compared with the control group, and with significantly higher neutrophils and CRP compared with non-recent COVID-19 group." (PMID 36325669, 2022). "It was found that the levels of D-dimer, FDP and CRP in cancer and COVID-19 patients were significantly higher than those in non-cancer cohorts(P<0.05)." (PMID 36439504, 2022). "CRP concentration was measured in the serum of total COVID-19 patients (with and without lymphopenia) and healthy control individuals using the ELISA technique following the manufacturer's guidelines (Demeditec, Germany)." (PMID 35721343, 2022). "Recent studies demonstrated that lopinavir trough concentrations were 3.5-fold higher in COVID-19 patients than in HIV-infected patients, which positively correlates with CRP values and was significantly lower when tocilizumab (IL-6 receptor antagonist) was pre-administered." (PMID 35185562, 2022). "Many studies have also demonstrated that T lymphocytes (T cell) (CD3+ CD4+ T cell and CD3+ CD8+ T cells) are reduced in COVID-19 and are significantly lower in SARS-CoV-2 severely ill patients in which high levels of C reactive protein (CRP) and IL-6 have been reported." (PMID 35336973, 2022). "When COVID-19 patients were segregated into subgroups, amongst the patients with a moderate disease, strong correlations were found between AAT and AGP (r = 0.91, p < 0.001), HP (r = 0.79, p < 0.01), hs-CRP (r = 0.72, p < 0.01), and CP (r = 0.89, p < 0.01)." (PMID 36514048, 2022). "Measurements of systemic inflammation, such as CRP, D-dimer, procalcitonin, and ferritin were elevated in the majority of hospitalized COVID-19 patients irrespective of race/ethnicity." (PMID 35715729, 2022). "C-Reactive Protein (CRP) levels were significantly elevated in children with MIS-C when compared with those with acute COVID-19, other infectious and non-infectious diseases and healthy control children." (PMID 36322537, 2022). "In the present study, we aimed to investigate clinical phenotypes of patients hospitalized due to COVID-19 and to examine the predictive value of NLR, PLR, neutrophil granulocytes, lymphocytes, platelets, and C-reactive protein (CRP) in a representative patient collective of the Swiss population." (PMID 35626265, 2022). "Meanwhile, the WBC count (p < 0.001), neutrophil percentage (p < 0.001), platelet count (p < 0.001), CRP level (p < 0.001), procalcitonin level (p < 0.001), and AST level (p = 0.015) were significantly lower in patients with COVID-19 compared to patients with KD." (PMID 35626814, 2022). "The lymphocyte level was lower, while the levels of NLR, LDH, CRP, IL-6, and IL-8 were higher in patients with severe COVID-19 than in those with non-severe symptoms." (PMID 35687545, 2022). "However, they were lower in viral controls (IL-6 4.61 pg/ml [IQR 2.09–16.51], CRP mg/l 3.3 [IQR 0.9–15.0], PCT 0.030 ng/ml [IQR 0.014–0.056]), than in COVID-19 with p-values again <0.001 for all comparisons." (PMID 35622838, 2022).
COVID-19 (continued). "The results revealed that the levels of CRP, D-dimer, and LDH, AUC more than 0.75, were valuable diagnostic biomarkers for distinguishing ARDS-COVID-19 from non-ARDS-COVID-19." (PMID 33861750, 2021). "Important laboratory values measuring the severity of COVID-19, such as White Blood Cell count, d-Dimer, and C-reactive protein, were not well documented in EHRs during the early stage of COVID-19 pandemic." (PMID 34848761, 2021). "The lower PLTP activity we observed in COVID-19 patients is consistent with the lower proportion of extra-pulmonary organ dysfunction (septic shock, lactatemia, RRT and creatininemia) and the lower acute phase response (CRP levels)." (PMID 34031519, 2021). "The blood C-reactive protein (CRP) level was 3+ but the chest x-ray showed no findings compatible with COVID-19." (PMID 34760109, 2021). "Several studies have reported a significant increase in neutrophil-to-lymphocyte ratio (NLR), C-reactive protein (CRP), and serum ferritin in COVID-19 patients with ischemic stroke, which could predict mortality in these patients." (PMID 33920904, 2021). "Higher values of CRP, ESR, IL-6, and β-2-glycoprotein antibodies as well as higher frequencies of CRP elevation and any Ig decrease were observed for post-COVID-19 patients compared to healthy controls (p = 0.009; p = 0.007; p = 0.004; p = 0.031; p = 0.007; p = 0.015, respectively)." (PMID 34722682, 2021). "Also in COVID-19 patients, reduction in PCT and CRP levels was observed in patients treated with tocilizumab." (PMID 34353339, 2021). "We investigated PCT and CRP kinetics in critically ill COVID-19 patients treated with dexamethasone (DEXA) with or without tocilizumab (TOCI), and assessed the value of these biomarkers to detect secondary infections." (PMID 34781995, 2021). "The group of severe COVID-19, in our study, had the highest mean value of CRP at admission although there was no statistical significance between the groups." (PMID 33854695, 2021). "A recent study showed that refractory COVID-19 patients had increased blood LDH and CRP levels." (PMID 33713401, 2021). "Taken together, endothelial dysfunction (elevated vWF level), with the release of fibrinolysis inhibitor PAI-1, and hyperimmune response (increased ESR, CRP, ferritin, and IL-6) with younger (higher H-IPF) activated platelets seem to be significant contributors to thrombogenesis in COVID-19." (PMID 34940584, 2021). "A marked decrease of the proinflammatory markers C-reactive protein (CRP), ferritin, and lactate dehydrogenase (LDH) was observed 7 days after CCP transfusion in a proof of concept single-arm multicenter trial conducted in Italy on 46 severe COVID-19 patients." (PMID 34452459, 2021). "Besides, pioglitazone reduces serum ferritin, CRP, and other pro-inflammatory cytokines in T2DM, thus reducing the likelihood of CS when COVID-19 is developed." (PMID 34124187, 2021). "Moreover, we found a prompt decrease in serum CRP, IL-6, IP-10, MCP-1, and IFN-γ levels in severe patients with COVID-19 who responded well to tocilizumab." (PMID 34631752, 2021). "In hospitalized individuals with COVID-19, colchicine did not affect C-reactive protein or cardiac troponin levels, although an improved time to clinical deterioration was reported." (PMID 33584343, 2021). "According to our findings, MHD patients with COVID-19 who experienced non-surviving outcome had more elevated CRP, IL6 and procalcitonin as well as fibrinogen levels at various points compared to survivors." (PMID 33967613, 2021). "Also, some studies showed that some frequent complications in severe and expired COVID-19 patients, such as shock, ARDS, acute kidney injury, and acute cardiac injury, were correlated with higher CRP levels." (PMID 33968148, 2021). "Furthermore, C-reactive protein (CRP), procalcitonin (PCT) and interleukin-8 (IL-8) concentrations were reduced in the patients with COVID-19 who received IVC." (PMID 34833042, 2021).
COVID-19 (continued). "They observed significant differences in white blood cell counts, C-reactive protein (CRP), and IL-6, and concluded that COVID-19 mortality may be due to a virus-related “cytokine storm”." (PMID 33467466, 2021). "A study from Wuhan included 377 patients and found age, neutrophils to lymphocytes ratio, CRP, and D-dimer as predictors of the severity of COVID-19, defined as severe pneumonia and non-severe pneumonia." (PMID 33620680, 2021). "In the study C-reactive protein (CRP) levels were higher in patients with low HDL-C, which indicated that HDL-C may hamper inflammation and thus have a protective effect against COVID-19." (PMID 34315474, 2021). "Indeed the reduced circulating levels of BPIFB4 in patients with severe disease (characterized by elevated levels of CRP and LDH) validate its prognostic significance for severity in patients with COVID-19." (PMID 34396395, 2021). "Specifically, severe COVID-19 patients are likely to present elevated levels of white blood cell (WBC), neutrophil counts, neutrophil-to-lymphocyte ratio (NLR), D-dimer, procalcitonin (PCT), C-reaction protein (CRP), and erythrocyte sedimentation rate (ESR)." (PMID 34423043, 2021). "This typically occurs in subjects with ARDS, where the exacerbated CRP increase and hyper ferrfitinemia are key for diagnosing MAS and are elevated in many serious cases of pneumonia due to COVID-19.The low survival rate of ARDS has been related to a sustained elevation of IL-6 and IL-1." (PMID 33776561, 2021). "Age, sex, BMI, race, COVID-19 disease severity, Charleston Comorbidity Index, COPD, C-reactive protein (>150 mg/L), interleukin-6 (>80 mg/L), ferritin (>2,000 ng/L), D-dimer (>2.0 mg/L), use of anticoagulation, use of corticosteroids, and smoking (current and former)." (PMID 34222281, 2021). "In a meta-analysis involving 21 studies indicated that inflammatory biomarkers including ESR and CRP were significantly increased in patients with both survivors and nonsurvivors COVID-19." (PMID 34775984, 2021). "We hypothesized that by using one simple biomarker (CRP), it would be possible to predict the likelihood of hospitalization and/or ARDS among suspected COVID-19 patients." (PMID 35011944, 2021). "In line with findings from recent studies probing blood immune cell and biochemical measurements in COVID-19 patients, we found elevations of innate immune cells (neutrophils and white cells) and pro-inflammatory indicators (C-reactive protein and LDH) in the blood of more severe COVID-19 cases." (PMID 33853691, 2021). "The presence of autoantibodies in COVID-19, specifically ANA and RF, has been correlated with CRP levels and shown to be higher overall than in uninfected controls, with targets involving immunomodulatory proteins including cytokines, chemokines, complement factors, and cell surface proteins." (PMID 33969248, 2021). "A positive correlation of increased LDH levels with the CRP and cardiac troponin I (cTnI) level and a negative correlation with lymphocyte count in severe COVID-19 patients were also reported." (PMID 34538093, 2021). "- Different from previous study, our study found that CRP did not predict the severity and death of diabetic patients after infected with COVID-19." (PMID 34164413, 2021). "COVID-19 patients not expressing CHRFAM7A had higher levels of CRP, more extended pulmonary lesions and displayed more pronounced lymphopenia." (PMID 34088975, 2021). "Knowledge of the kinetics of IL-6 did not offer enhanced predictive value for disease severity in COVID-19 over common investigations such as CRP and vital signs." (PMID 33815405, 2021). "When comparing laboratory indexes between COVID-19 patients with or without AKI, LDH, BUN, and CRP were associated with increased risk of AKI, in which BUN shows the highest OR (1.12, 95% CI, 1.04–1.20)." (PMID 34136484, 2021).
COVID-19 (continued). "The MASP-2 inhibitor narsoplimab was associated with rapid and sustained reduction of circulating endothelial cell counts and serum IL-6, IL-8, CRP, and lactate dehydrogenase (LDH) in six patients with COVID-19 on mechanical ventilation, correlating with clinical improvement." (PMID 34924021, 2021). "Recent studies have shown that combined biomarkers, including PNI, SII, NLR, CRP/Alb ratio, and PLR, are indicators of systemic nutritional status and inflammation, which are closely related to the prognosis and severity of COVID-19." (PMID 34900028, 2021). "Referring to Pal and Bhadada, DM is also a pro-inflammatory state, and COVID-19 patients with DM showed significantly higher serum levels of interleukin-6 (IL-6), C-reactive protein and ferritin than those without DM." (PMID 34416856, 2021). "A recent meta-analysis has demonstrated that patients with severe COVID-19 tend to present increased leukocyte and neutrophil counts, neutrophil–lymphocyte ratio, PCT and CRP levels, and a decreased number of total lymphocytes, among parameters, compared to nonsevere individuals." (PMID 34207873, 2021). "A separate study reported a decrease in baseline CRP levels in COVID-19 (+) patients in whom the severity of depression symptoms decreased compared to COVID-19 (+) patients in whom CRP and depression symptoms were not significantly reduced." (PMID 34575258, 2021). "Adverse events/severe adverse events, COVID-19 symptoms, SARS-Cov-2 virus test, blood SARS-Cov-2 IgM and IgG antibodies tests, blood cytokine and inflammatory (CRP, IL_6, IL-10, TNFα) tests and disease severity evaluation for 6 months after the last dose of AdMSC infusion for the SG and CG." (PMID 33815867, 2021). "In terms of laboratory findings, an increased erythrocyte sedimentation rate (ESR) and elevated levels of C-reactive protein (CRP), lactate dehydrogenase (LDH), ferritin, interleukin 6 (IL-6), and tumor necrosis factor-α (TNF-α) are commonly observed in patients with COVID-19." (PMID 34295915, 2021). "Among biological variables related to anemia, inflammation markers (ferritin, CRP) were the only significant differences between anemic patients from COVID-19 to non-COVID-19 groups." (PMID 33912067, 2021). "We also integrated the role of CRP and NLR as predictive markers in COVID-19." (PMID 34069451, 2021). "Among them, compared to the non-COVID-19 cohort, COVID-19 patients demonstrated much higher levels of CRP and LDH, but a dramatically lower level of TnT and procalcitonin." (PMID 34485324, 2021). "COVID-19 patients with periodontitis had higher white blood cell and CRP levels compared to those without periodontitis, suggesting that periodontitis contributes to COVID-19 severity via systemic inflammation." (PMID 34950607, 2021). "At present, one RCT is aiming to evaluate the efficacy of PJ on inflammatory parameters, C-reactive protein (CRP), interleukin 6 (IL-6), erythrocyte sedimentation rate (ESR), and complete blood count (CBC) in mild to moderate COVID-19 patients (IRCT20150711023153N2)." (PMID 34796029, 2021). "A systemic inflammatory storm in COVID-19 may also contribute to the amplification of the GBS’s dysimmune process, related to increased blood inflammatory markers (e.g., CRP, IL-6, TNF-α, and IL-1)." (PMID 34078305, 2021). "Meantime, AST, LDH, CRP and PCT are useful prognostic marker for COVID-19." (PMID 33663273, 2021). "LDH and CRP appear to reflect the respiratory destress consequent to the abnormal inflammation status induced by SARS-CoV-2 infection and predict respiratory failure in COVID-19 patients." (PMID 35056076, 2021). "Recently, studies with small sample sizes have shown a significant increase in the CRP/Alb ratio in patients with severe COVID-19 and nonsurvivors." (PMID 34900028, 2021).
COVID-19 (continued). "Inflammatory and coagulation markers such as C-reactive protein, interleukin-6, and D-dimer were elevated in patients with COVID-19; however, they were not routinely measured for patients with influenza, limiting any comparisons." (PMID 34307971, 2021). "Our aim was to prospectively investigate the safety and efficacy profile of tocilizumab administration at the time point that PaO2/FiO2 < 200 was observed in hospitalized patients with COVID-19 irrespective of CRP and other markers of systemic inflammation." (PMID 34937570, 2021). "As such, CRP and SAA may be sensitive indices for detecting COVID-19 and classifying disease severity." (PMID 33627079, 2021). "In univariate analysis, risk factors influencing overall survival in the total population were age (p < 0.0001), performance status (p < 0.0001), time from HCT to COVID-19 (p = 0.04), ISI intermediate + high vs. low (p = 0.0008), ANC (p = 0.018), and the ALC/CRP ratio (p = 0.009)." (PMID 34079042, 2021). "Severe patients with COVID-19 were suggested to have higher levels of CRP, D-dimer, and LDH and a lower level of albumin than non-severe patients." (PMID 34021206, 2021). "After August, in replace of tocilizumab, we treated severe cases of COVID-19, who required oxygen supply, with dexamethasone (6 mg/day for up to 10 days), regardless of serum concentrations of CRP or ferritin." (PMID 34631752, 2021). "However, most studies agree that people infected with COVID-19 are likely to show increased levels of ESR and CRP, thrombocytopenia, and leukopenia, as was the case in our patient." (PMID 34321077, 2021). "Ferritin, D-dimer, CRP, NLR, cytokine (IL-18 and IL-10), and cytokine receptor (IL-6, IL1-Ra, and sCD25) test results combined with clinical data can contribute to the early identification of critical COVID-19 patients." (PMID 34422145, 2021). "Furthermore, the levels of inflammatory markers (CRP, d-dimer and neutrophil-to-leukocyte ratio), creatinine level and AST level were higher and albumin levels were lower in the COVID-19-positive group than in the COVID-19-negative group." (PMID 34190873, 2021). "Considering the objectives of our study, we highlight that there were significant, direct correlations between CCl2, galectin-3, PON1 concentration, CRP, IL-10, IL-6, and angiotensin II in COVID-19 positive patients, but not in the COVID negative ones." (PMID 34205807, 2021). "The RECOVERY trial enrolled severe COVID-19 hospitalized patients with hypoxemia, with or without mechanical ventilation, and C-reactive protein (CRP) level ≥75 mg/L." (PMID 34659200, 2021). "However, there were significantly higher levels of IL-6 and CRP in patients with immune dysregulation and MAS compared to patients with intermediate COVID-19." (PMID 34452063, 2021). "Previous studies suggested that CRP could be an independent risk factor for death in diabetic patients with COVID-19; however, according to our data, we believe that CRP may be an important risk factor for mortality risk in all patients with COVID-19, independent of diabetes mellitus status." (PMID 34164413, 2021). "Notably, our signature also discriminated between bacterial infection and COVID-19 with an AUROC of 0·953, sensitivity of 88·6%, and specificity of 94·1%, whereas CRP levels demonstrated considerable overlap between these groups." (PMID 34423323, 2021). "Furthermore, the use of immunomodulatory treatments in critically ill COVID-19 patients considerably reduces the value of PCT and CRP for detection of secondary infections, reflecting a false-negative finding." (PMID 34353339, 2021). "Assessment of infection-related biomarkers (CRP, ESR) and cytokine profile (IL-2R, IL-6, IL-8, IL-10, IL-1β, TNF-α, procalcitonin) on admission showed a proinflammatory state in hemodialysis patients with COVID-19." (PMID 33967613, 2021). "Based on these evidences, CRP, IL6 and procalcitonin levels may serve as potential markers for predicting progression of MHD patients with COVID-19." (PMID 33967613, 2021).